EPHA4 (EPH receptor A4)
Diseases named in the same sentence as EPHA4 in open-access papers (continued):
Sharing a sentence is not in itself a finding about the gene and the disease.
tumor (continued). "Our findings confirmed that IGF1 administration could enhance the tumor growth of EphA4‐deleted mice up to a level similar to that observed in control WT mice, but could not enhance the metastatic tumor foci of EphA4‐deleted mice up to the WT level." (PMID 26923183, 2016). "However, knockout studies in mouse models lacking EphA4 and EphA7 revealed no significant impact on tumor size, suggesting that these receptors may not play a central role in tumor growth." (PMID 41200151, 2025). "The discrepancy may mainly come from tumor or cell-type specificity because HT-29 cells, unlike 4T1 cells, express low or undetectable levels of EphA4 64, thus stopping RNase1 from binding to and activating EphA4 signaling in HT-29 cells." (PMID 37416781, 2023). "Given the parallel increase in EphA4 protein levels and its phosphorylation status, we questioned whether hyperactivation of EphA4 plays a dominant role in stimulating tumor growth in the absence of cancer cell EphB4 and whether we can reverse it by using the pharmacological intervention." (PMID 35725568, 2022). "Based on our results, we concluded that EphA2, EphA3, EphA4, and EphA5 were down-regulated in BCs, and high expression levels of these genes indicated better RFS, suggesting that EphA2, EphA3, EphA4, and EphA5 act as tumor suppressors in BC and could be new biomarkers for its prognosis." (PMID 34221956, 2021).
cancer (51 papers, 2008 to 2024). A tumor composed of atypical neoplastic, often pleomorphic cells that invade other tissues. "High expression levels of EphA4 have been observed in various cancers associated with oncogenic functions." (PMID 37416781, 2023). "Loss of EphB4 on the cancer cells elicits a robust compensatory effect mediated by EphA4 and results in an influx of immunosuppressive regulatory T cells (Tregs)." (PMID 35725568, 2022). "Cisplatin chemotherapy for cancer causes demyelination as a side effect,probably through activation of EphA4 by ROS-induced tyrosine phosphorylation." (PMID 35271507, 2022). "We found that mutation of L920 to phenylalanine (L920F) potentiates EphA4 autophosphorylation and signaling, making it the first documented EphA4 cancer mutation that increases kinase activity." (PMID 34139238, 2021). "Although EphA4 is highly expressed in the central nervous system, EphA4 has also been implicated in cancer progression." (PMID 26923183, 2016). "In stage II and III cancer, EphA4 and EphA2 were both significantly associated with shorter survival (p = 0.007 and 0.019), but only EphA2 was an independent prognostic factor (HR, 2.6; 95% CI, 1.1-6.3; p = 0.039)." (PMID 23738943, 2013). "However, the precise role of EphA4 in cancer progression and the mechanisms underlying the potential oncogenic activity of EphA4 are poorly understood." (PMID 34139238, 2021). "One such interaction involves the myeloid cell marker CD11b on TAMs and CD90 on cancer stem cells, accompanied by EphA4 and epinephrine leading to the release of several other immunosuppressive cytokines that help maintain cancer stemness and survival." (PMID 36627890, 2022). "Epithelial-rich subtypes showed higher EphA6 cytoplasmic H-score (B2/B3, carcinoma) (p < 0.001) and stronger EphA4 H-score (B3, carcinoma) (p = 0.011)." (PMID 34943502, 2021). "The interactions between macrophages and CSCs mediated through THY1 and EPH receptor A4 (EPHA4) activate NF-κB and sustain cancer stemness." (PMID 33371274, 2020). "At least as a regulator of adherens junctions, EphA4 now emerges as an attractive therapeutic target to prevent cancer cell dissemination and metastasis, including strategies aimed at overcoming chemo- and/or radioresistance." (PMID 30639848, 2019). "A recent report indicates that interactions between EphA4 on cancer cells and ephrin on macrophages leads to a CSC state for cancer cells without stimulation by external ligands such as LPS and HMGB1." (PMID 28969049, 2017). "EphA4 has been found to play a role in cancer biology and in the pathogenesis of several neurological disorders." (PMID 28526745, 2017). "In view of EphA4's role in normal physiology as well as in cancer and neurodegeneration, the generation of potent and selective antagonists against this receptor is of great interest." (PMID 28526745, 2017). "EphA4 belongs to the Eph receptor tyrosine kinase family and has been demonstrated to play roles in different types of human cancers." (PMID 27487126, 2017). "Our results indicate that the EphA4‐deleted host can potentially change the crosstalk of humoral and cell–cell contact‐mediated signals in cancer development and play a critical role to inhibit the growth of even more malignant stem‐like cancer cells." (PMID 26923183, 2016). "The mouse models were generated by breeding the ND2-SmoA1 mice (Fred Hutchinson Cancer Research Center, Seattle, WA, USA) used in previous studies with ephrin-A5−/− mice or EphA4−/−EphA7−/− mice." (PMID 26345456, 2015). "Consistent with the finding that CIL drives embryonic cell dispersal during development, we show here that EphA receptors mediate CIL via Vav2 and RhoA and that EphA2/EphA4 can regulate cancer cell dissemination from dense cancer cell populations." (PMID 24795148, 2014). "After 6 days, control siRNA-treated cells migrated out of the cancer cell mass into the surrounding collagen gel but EphA2/EphA4 knockdown cells displayed significantly less invasion." (PMID 24795148, 2014).
cancer (continued). "Overexpression of EphA4 is observed in many human cancers, including prostate, breast, gastric, and pancreatic tumors." (PMID 24265799, 2013). "In the present study, EphA2, ephrinA1, and even EphA4 were also expressed in vascular endothelial cells existing in cancer tissue." (PMID 23738943, 2013). "High levels of EphA4 RNA expression are correlated significantly with reduced overall survival of cancer patients." (PMID 24265799, 2013). "Because researchers observed a positive correlation between MAPK pathway activity and PD-L1 expression in human cancer cells, we asked whether activation of EphA4/ERK signaling by RNase1 affects PD-L1 protein levels in HCCs." (PMID 38307859, 2024). "EphA4 may also affect cancer malignancy, but the regulation and effects of EphA4 signaling in cancer are poorly understood." (PMID 34139238, 2021). "The ligation of CD90 to ephrin type-A receptor 4 (EphA4) on cancer cells induced downstream signaling that resulted in the production of IL-6, IL-8, and granulocyte-macrophage colony-stimulating factor (GM-CSF), thus facilitating the maintenance of the stem-cell-like niche." (PMID 32117287, 2020). "The comparison of AEM to advanced carcinoma was significant in case of EPHA4 as well (p < 0.001)." (PMID 33322258, 2020). "In cancer with poor prognosis, EphA4 and E-cadherin appear to be regulated in opposite ways." (PMID 30639848, 2019). "Upregulation of EPHA4 was observed in various cancers, including CRC." (PMID 30175151, 2018). "A potential role for EphA4 in human cancer is also receiving increasing attention." (PMID 24265799, 2013). "Expressions of EphA2, EphA4, and ephrinA1 were mainly observed in the cytoplasm of cancer cells." (PMID 23738943, 2013). "Furthermore, we identified several RNA-binding proteins, including HuR, that interact with these clusters, and we show that EfnA2, EphA2, and EphA4 are direct posttranscriptional targets of HuR in cancer cell lines." (PMID 18648668, 2008). "The ephrin type‐A receptor 4 (EPHA4) protein on the surface of TAMs is upregulated during EMT and binds directly to the receptor on cancer cells, which activates the NF‐kB pathway in cancer cells to facilitate the maintenance of homeostasis in the CSCs." (PMID 34914196, 2022). "We found a number of genes involved in G protein-coupled receptor signaling (ARAP2, LPHN2, LPHN3, EPHA4, ADGRL2, and GPC5) consistent with observations in pan-cancer studies." (PMID 35538064, 2022). "EPHA4 showed similar expression in AEC and advanced carcinoma, while FN1 showed down-regulation of expression in AEC and up-regulation in advanced carcinoma." (PMID 33322258, 2020). "Levels of MFNG in this subgroup of tumors also determined the transcriptional status of several Notch target genes such as NKD1, DLX3, EREG, EPHA4, or IL7R, known to be relevant for cancer progression." (PMID 30065304, 2018). "In other cancer types, the co-operation of EphA2 with PI3K/Akt signaling and EPHA4 with FGFR signaling have similarly been shown to promote migration and invasion." (PMID 29101386, 2017). "Another study has shown that Eph receptor A4 (EphA4) is overexpressed in PDAC and promotes cancer cell growth, suggesting that EphA4 is a likely prognostic factor or a molecular target for therapy of PDAC." (PMID 26516928, 2015). "Signaling pathways mediated by EphA4 and FGFR play critical roles in promoting the proliferation and migration of embryonic neural stem cells and of cancer cells." (PMID 24265799, 2013). "Among them, ephrin receptor EPHA4, actin binding LIM-proteins ABLIM1 and ABLIM2, semaphorin SEMA7A and glial neurotrophic factor GFRA2 genes, which are involved in axon guidance, are commonly repressed in cancer cells by DiPRO1 and SIX1." (PMID 39009887, 2024). "In fact, the roles of EphA4, including the related signaling pathways in several cancers, have not been studied extensively." (PMID 26516928, 2015).
cancer (continued). "Two of the genes (KIF17 and ATP8A2) showed no methylation in either cancer or matched tissues, and eight genes (EPHA4, OVOL1, UTF1, ADAM8, BOLL, FOXE3, GUCY1A2, and ADCY5) were equally methylated in the two groups." (PMID 21625442, 2011). "In addition, we also identified EPHA4 as a common kinase in ALS and cancers." (PMID 36590916, 2022). "Therefore, we suggest that EphA2 and EphA4 can signal via Vav2 and RhoA leading to microtubule destabilisation and subsequently cell–cell repulsion, although we cannot rule out additional signalling events regulating cancer cell repulsion downstream of EphA receptors." (PMID 24795148, 2014).
infection (10 papers, 2016 to 2025). The state of being infected such as from the introduction of a foreign agent such as serum, vaccine, antigenic substance or organism. "Another Eph receptor possibly involved in KSHV infection is EphA5 as transduction of an EphA5 (or an EphA4) construct was able to rescue infection in cells that were deficient for EphA2." (PMID 33430066, 2021). "Finally, we determined whether overexpression of EphA4-venus by adeno-associated virus (AAV) infection in the medial PFC caused the depression-like phenotype." (PMID 28769056, 2017). "Nevertheless, overexpression of EphA4 led to an equivalent species-independent increase in MHV68 ORF59-GFP infection." (PMID 40501621, 2025). "Expression of EphA4 had a comparably less pronounced effect on MHV68 infection of ~8-fold enhancement compared to empty vector." (PMID 40501621, 2025). "We found that both EphA2 and EphA4 play a role in KSHV fusion and infection, since EphA2-EphA4 double-knockout cells had the greatest decrease in fusion activity and infection compared to single-knockout cells." (PMID 30782663, 2019). "Transfection of the double-knockout cells with EphA2 or EphA4, and especially both EphA2 and EphA4, rescued infection." (PMID 30782663, 2019). "Flow cytometry showed increased infection of KSHV in the presence of either EphA2 or EphA4 and higher levels of fusion when both EphA2 and EphA4 were transfected." (PMID 30782663, 2019). "When EphA2 and EphA4 were individually transfected into the double-knockout cells, infection with KSHV was partially rescued compared to levels observed in HEK293T cells." (PMID 30782663, 2019). "The level of infection in EphA2-expressing cells was just above background levels, in contrast to the EphA4-expressing cells, in which the level of infection was higher." (PMID 30782663, 2019). "Using RNA-seq analysis, we found that EphA4 is expressed in B cells, fibroblasts, epithelial cells, and endothelial cells suggesting a role for EphA4 in the infection of epithelial cells." (PMID 30782663, 2019). "There is evidence that EphA4 may also be an entry receptor for KSHV; EphA4 expression has been detected in KSHV target cells and an EphA2-EphA4 double-knockout resulted in a greater reduction in infection than EphA2 or EphA4 single knockouts." (PMID 33430066, 2021). "We identify EphA4 and EphB3 as direct interaction partners of the MHV68 gH/gL complex that facilitated MHV68 infection in different cell types from humans and mice." (PMID 40501621, 2025). "In the ACE2-positive condition, overexpression of almost all cDNAs enhanced pseudovirus entry with CD7, EPHA4, LRCC8D, and LGMN overexpressing lines showing greater than 2-fold increases in Spike-mediated infection." (PMID 40674406, 2025). "Comparisons between latent and active infection also showed a similarly low variation of AUROC values (DOCK9: 0.86–0.95; EPHA4: 0.91–0.96; NPC2: 0.8 –0.98)." (PMID 34685683, 2021). "As EphA4, EphA5, and EphA7, which are low-affinity receptors for KSHV, are expressed in B cells, these receptors play a crucial role in the infection of B cells by KSHV16,18,19,30." (PMID 33235207, 2020). "To confirm EphA4 is important for KSHV fusion and infection, we generated EphA2 and EphA4 single- and double-knockout cells." (PMID 30782663, 2019). "In the current studies, we have found that EphA4 promotes KSHV glycoprotein H/glycoprotein L (gH/gL)-mediated fusion and infection better than does ephrin A2 (EphA2) in HEK293T cells, indicating that EphA4 is a new KSHV entry receptor." (PMID 30782663, 2019). "Knockout of both EphA2 and EphA4 greatly decreased fusion and infection of KSHV, while overexpression of EphA2 and EphA4 alone or together rescued the fusion and infection of EphA2-EphA4 double-knockout cells." (PMID 30782663, 2019). "Fusion and infection of KSHV were rescued in the EphA2-EphA4 double-knockout cells upon overexpression of EphA2 and/or EphA4." (PMID 30782663, 2019).
infection (continued). "Ectopic expression of EphB3 of human and mouse origin exhibited the strongest enhancement of MHV68 ORF59-GFP infection, leading to an ~ 20-fold increase in GFP+ cells.Expression of EphA4 had a comparably less pronounced effect on MHV68 infection of ~8-fold enhancement compared to empty vector." (PMID 41118409, 2025). "It was further determined that multiple Eph receptors, including EPHA4 and EPHA5, could rescue KSHV infection, and interestingly, EPHA4 overexpression greatly enhanced infection, suggesting its important role in epithelial cell infection." (PMID 33477296, 2021). "Since fusion levels are not altered in the EphA2 and EphA4 kinase-dead mutants, it is likely that the kinase function is important for infection by functioning in endocytosis following virus binding." (PMID 30782663, 2019). "EphA4 promotes both KSHV cell-cell fusion activity and infection." (PMID 30782663, 2019). "Interestingly, differences in apparent saturation binding of EphA4 and EphB3 observed in co-precipitation and ELISA experiments did not correlate with augmentation of MHV68 infection of Raji cells." (PMID 41118409, 2025). "Interestingly, differences in binding affinity of EphA4 and EphB3 observed in co-precipitation and ELISA experiments did not correlate with augmentation of MHV68 infection of Raji cells." (PMID 40501621, 2025).
neurological disorders (5 papers, 2017 to 2023). "Treating neurological disorders by targeting EphA4 implies using substances that are able to penetrate the blood brain barrier (BBB) to reach their target." (PMID 28526745, 2017). "We propose that EphA4 manipulation could be a promising therapeutic method for this kind of disease and develop clinical treatments for a variety of neurological diseases." (PMID 37519758, 2023). "However, as EphA4 is a promiscuous receptor, targeting EphA4 by blocking the interaction with all ephrin ligands might be the most efficient therapeutic strategy against neurological diseases." (PMID 28526745, 2017).
neurodegenerative disease (3 papers, 2018 to 2023). A disorder of the central nervous system characterized by gradual and progressive loss of neural tissue and neurologic function. "The present findings provided a novel insight into the functional role of direct interaction of EphA4 and PDGFRβ in neurogenesis, implicating its potential use for treating neurodegenerative diseases." (PMID 32116646, 2020). "Our aim of this study is to identify new EphA4 inhibitors as prospective therapy for various neurodegenerative diseases." (PMID 29743517, 2018).
EPHA4 also shares sentences with these, for which no sentence is quoted: lymphoproliferative disorder (3 papers); schizophrenia (3); bipolar disorder (2); craniosynostosis (2); invasive breast carcinoma (2); lung squamous cell carcinoma (2); mood disorder (2); + T-cell lymphoma (1); acute myeloid leukemia (1); adenocarcinoma (1); amyloid (1); Arthritis (1); astrocytoma (1); autism (1); autism spectrum disorder (1); Autoimmunity (1); B-cell CLL (1); B-cell lymphoma (1); brachydactyly (1); cerebral malaria (1); chordoma (1); Cirrhosis (1); clear cell renal cell carcinoma (1); colorectal tumors (1); corticotropic adenomas (1); cutaneous T-cell lymphomas (1); Dystonia (1); follicular lymphoma (1); gastric adenocarcinoma (1); glaucoma (1).
A further 31 diseases each share a sentence with EPHA4 in 1 paper.